CD4 (CD4 molecule)
Diseases named in the same sentence as CD4 in open-access papers (continued):
Sharing a sentence is not in itself a finding about the gene and the disease.
diabetes (continued). "This study performed a longitudinal analysis of a comprehensive panel of 22 innate and adaptive immune cell phenotypes, including differentiated and senescent CD4+ and CD8+ cells, with incident diabetes risk among a U.S. community‐based population of older adults." (PMID 36333945, 2023). "CD4+ T lymphocytes play the core role in the disease process of type 1 diabetes mellitus." (PMID 37373070, 2023). "We found that diabetes and CD4 count were independent factors that influenced the results of LAM." (PMID 38145052, 2023). "Diabetes, non-Hispanic ethnicity, and nadir CD4 counts were independently associated with impaired HRQOL in PWH." (PMID 36763643, 2023). "Furthermore, co-adoptive transfer of these e-B cells particularly regulated antigen-specific CD4+ T cells, reduced insulitis, and provided protection from diabetes in an adoptive transfer model of autoimmune diabetes." (PMID 37731505, 2023). "Prior studies have linked WM disease to both HIV disease-related factors (e.g., lower CD4+ T-cell nadir, longer duration of HIV infection, as well as CD4+ T-cell recovery) and comorbidities (e.g., hepatitis C virus (HCV) seropositivity, diabetes, and cerebrovascular risk factors)." (PMID 38140650, 2023). "It is probable that h145CSA being superior to h145chIgGAA in the reversal of diabetes is due to its efficiency in reducing pathogenic CD4+IFN-γ+ T cells and increasing the Treg/Th1 ratio without altering the percentage of Treg cells." (PMID 37600814, 2023). "Patients with diabetes mellitus have impaired function of both CD4+ and CD8+ T cells." (PMID 38046568, 2023). "Actually, the impaired immune state in diabetes is characterized by an initial interruption in the activation of Th1 CD4+ T cell-mediated immunity and late hyperimmune response, which may contribute to cytokine storm dominated by IL-6." (PMID 36123740, 2022). "In addition, to gain more about how CD4+ T cells affect diabetes, Pauken transferred a small number of naive CD4+ T cells from BDC2.5 mice into prediabetic NOD mice, allowing the cells to be activated by endogenous autoantigens." (PMID 36405706, 2022). "It has been suggested that β-cell antigens might be similar to these viral antigens, and they could promote the activation of diabetes-preventive CD4+ CD25+ Tregs (specific for these antigens)." (PMID 35894054, 2022). "Hypertension and diabetes were the most common stroke risk factors (73.47% and 28.57%, respectively), as well as a low cluster of differentiation 4 (CD4) count in participants with HIV+ diagnosis (n = 9; median CD4 count: 130)." (PMID 35169551, 2022). "Although CD4+ T cells are essential for the triggering and progression of diabetes, T1D development requires important contributions from cytotoxic CD8+ T cells that destroy β cells of the islets of Langerhans, leading to insufficiency of circulating insulin in NOD mice." (PMID 35502705, 2022). "Immune cells play an important role in the development of inflammation in type 1 diabetes mellitus, so we want to explore the changes of CD4+ T cells and macrophages in vivo, which can provide an experimental basis for immunotherapy based on CD4+ T cells and macrophages." (PMID 36056051, 2022). "Overall, our results indicate that NOD Vγ4+ γδ T cells inhibit the development of diabetes, and suggest that the process by which they do so involves IL-17 production and/or promotion of regulatory CD4+ αβ T cell (Treg) development in the pancreatic lymph nodes." (PMID 36291615, 2022). "Additionally, both groups displayed CD4+ T cell insulitis around the islet grafts, supporting that diabetes was due to islet graft destruction by adoptively transferred T cells." (PMID 35015736, 2022). "PFK15 treatment has been reported to increase the expression of PD-1 and LAG-3(lymphocyte-activation gene 3) on CD4 T cells and prevent the development of diabetes via inhibiting glycolysis utilization of diabetogenic CD4 T cells and reducing T cell responses to β cell antigen." (PMID 36704045, 2022).
diabetes (continued). "It has been shown that the CD4+ number differs in patients with diabetes combined with osteoporosis compared to patients with diabetes alone, inflecting the altered T cell subsets may be involved in developing diabetic osteoporosis." (PMID 36147571, 2022). "Transfer of GAD TCR‐transduced primary human CD4+ T cells HLA DR4 restricted causes insulitis without overt diabetes." (PMID 35498419, 2022). "The resistance of IFN-γ-R deficient animals to CD4+ T-cell mediated diabetes was shown to be primarily due to a lack of IFN-γ-R expression by β-cells." (PMID 33727573, 2021). "Considering the elevated levels of CD52 expression in the adipocytes of obese and obese T2DM patients, it is likely that this may lead to an increase in the ratio of CD4+CD52high T cells to CD4+CD52low T cells, thereby promoting the development of diabetes." (PMID 33705353, 2021). "To further confirm whether CD52 is involved in the pathogenesis of diabetes, we performed microarray analyses of CD4+CD52high T cells and CD4+CD52low T cells based on GSE94815." (PMID 33705353, 2021). "Age-affected 18 variables include comorbidity, hypertension, diabetes, lymphocyte, CD4+ and CD8+ T cells, IL8, TNFα, eGFR, hemoglobin, albumin, CK-MB, onset to admission, onset to PCR negative, discharged, secondary infection, acute kidney injury, and acute liver injury." (PMID 34025688, 2021). "Moreover, the adoptive transfer of diabetic CD4+T cells and MDSC to NOD/SCID mice significantly reduced the incidence of diabetes caused by single-transferred CD4+T cells, further clarifying that MDSC delayed diabetes by inhibiting T cells." (PMID 34975496, 2021). "CD4+ CD28null T-cell population is increased in both type 1 (T1D) and type 2 (T2D) diabetes." (PMID 34680058, 2021). "The protective effect of SE extract in MLDS-induced diabetes could be partly due to a decrease of CD4+and CD8+ T cells and an increase of Treg cells resulting in an inflammation reduction in the pancreatic islets." (PMID 34455723, 2021). "However, NAC can increase the infiltration of CD4 and CD8 T lymphocytes in the pancreas, causing the destruction of beta cells and consequently aggravating the effects of diabetes on tissues." (PMID 34099835, 2021). "However, the onset rate of diabetes reached 100% when lymphodepletion was performed through CTX administration before the transfer of activated Smarta CD4+ T cells." (PMID 33923792, 2021). "In the multivariate Cox hazard model, a decreased count of CD4+ TNaïve cells along with older age, history of diabetes, history of CVD, as well as elevated white blood cell count and NT-proBNP was independently associated with CVEs (HR 0.430, 95% CI 0.253–0.731, p = 0.002)." (PMID 33815398, 2021). "During the pathogenesis of diabetes, CD4+T cells induced DCs to effectively stimulate CD8+T cells." (PMID 34975496, 2021). "As diabetes progresses, CD4+ and CD8+ T cells infiltrate and destroy the pancreatic islet β cells." (PMID 34433860, 2021). "Consequently, PD-1 seems to regulate islet-reactive CD4+ T cells in a cell-intrinsic manner, by inhibiting their proliferation, limiting pancreas infiltration, and protecting them from diabetes." (PMID 33672515, 2021). "CATG small interfering RNA used in the pre-diabetic mellitus stage of non-obese diabetic mice improved the function of islet beta cells, reduced islet inflammation and beta cell apoptosis, and lowered the activation level of CD4+T cells, slowing down the progression of diabetes." (PMID 35058920, 2021). "Advanced age, female sex, obesity/adiposity, hyperuricemia/gout, longer duration of HIV, CD4 count less than 200 cells/mL, hyperkalemia, dyslipidemia, hypertension, diabetes mellitus, smoking, consumption of alcohol and herbal medication, self-medication were associated with increased odds of CKD." (PMID 32967645, 2020). "In our immunocompetent NOD hosts, transfer of highly purified CD4+ cells from diabetic donors caused diabetes in all α4+, yet none of the α4-/- recipients." (PMID 33291571, 2020).
diabetes (continued). "Shortness of breath at admission, past histories of diabetes and heart disease, and abnormalities in the 28 indicators, such as CD4 percentage and CRP, indicate that the patient is already severely ill or has a significant risk of progressing to severe conditions." (PMID 32766268, 2020). "Thus CD4+ T-cells are actually quite efficient at inducing diabetes if they can recruit and instruct additional α4+ host immune cells, presumably CD8+ lymphocytes." (PMID 33291571, 2020). "Of note, one person with diabetes had a significant proportion of CD4+ MAIT cells (47.2%)." (PMID 32231670, 2020). "Having CD4 count less than 200 cells/μl at recruitment was associated with increased risk of diabetes (RRR = 1.79 [95%CI, 1·13–2.83]) but not prediabetes." (PMID 32267855, 2020). "To determine whether measurement of NB accumulation by contrast-enhance ultrasound can report on therapeutic diabetes reversal we treated AT mice at 2 weeks post-transfer with antiCD4 antibody to deplete CD4+ T cells." (PMID 32382089, 2020). "CD4 count <200 cells/μl was associated with increased risk of diabetes (RRR = 2.71 [95%CI, 1.36–5.38] but not prediabetes." (PMID 32267855, 2020). "Additionally, in murine TLR9-/- models it has been shown that an elevated expression of CD73 on immune cells was associated with the production of anti-inflammatory cytokines by CD4+ T cells and delayed diabetes development." (PMID 32707842, 2020). "Our results demonstrate that TLR4 blockade decreases CD4+ T lymphocyte activation and auto-antigen-specific proliferation both in vitro and in vivo, decreases the infiltrative insulitis and finally prevents the onset of spontaneous diabetes." (PMID 31852918, 2019). "Also, in other manifestation forms of the metabolic syndrome, such as diabetes and obesity, CD4 and CD8 T cells seem to play a disease worsening role." (PMID 30949049, 2019). "Co-transfer of CD4+CD25+ Tregs isolated from spleens of vehicle-treated NOD mice with diabetic splenocytes resulted in a higher incidence of diabetes in recipient mice (14 out of 16) than that found in a animals given cells from vaccine-treated mice (10 out of 16)." (PMID 30863412, 2019). "Higher prevalence of hypertension was also observed in men than in women and in those with longer duration of HIV infection, longer duration of ART exposure, a family history of hypertension, high BMI, low CD4 count, diabetes mellitus, or impaired renal function (low eGFR)." (PMID 31929895, 2019). "In addition, CD137 had a diabetes protective function when expressed in CD4+ T cells, likely due to the immunosuppressive activity of soluble CD137 produced by Tregs." (PMID 29527189, 2018). "In addition, transient overexpression of Zbtb32 in islet-specific CD4 T cells delayed diabetes development, and decreased both proliferation and IFNγ production in islet-specific CD4+ T cells." (PMID 29707204, 2018). "Among HIV+ persons, nadir CD4 count <200 cells/mm3 was associated with approximately two-fold greater odds of AF/AFL; this persisted even after adjustment for age, sex, race, BMI, diabetes, hypertension, smoking, and COPD (adjusted OR 1.98, 95% CI 1.21–3.25)." (PMID 29558525, 2018). "Furthermore, long-term administration of androgen or its derivatives to young female NOD mice resulted in a decrease in the percentage of CD4+ T cells in peripheral blood mononuclear cells and the incidence of diabetes." (PMID 29867762, 2018). "It has been reported that CD4+ T cells are required for the initiation of diabetes and that the Th1 cytokines IFN-γ and TNF-α may contribute to islet β cell death." (PMID 29844327, 2018). "Among the 2056 patients, 78% were women, median age was 35 years, and median CD4 count was 464/mm3, 6.8% were obese, 6.3% had hypertension, 7.8% were smokers (1.8% women, 26.8% men), 19% had Total Cholesterol (TC) >5mmol/L, and 1% diabetes at baseline." (PMID 28582393, 2017).
diabetes (continued). "Thus, both ICOSL−/−CIITA−/− and ICOSL−/−β2m−/− NOD mice were protected from diabetes, but only ICOSL−/−CIITA−/− NOD mice were protected from neuromuscular autoimmunity, confirming the major pathogenic role of CD4+ T-cells in the neuromuscular model." (PMID 28424681, 2017). "The CD4+ T-cell subsets have divergent CD4+ T-cell responses and may contribute to the chronic autoimmune responses in type 1 diabetes mellitus." (PMID 28420440, 2017). "Thus, our novel findings in established T2D extend our previous observations in patients at risk of developing T2D that the systemic presence of IL-21R+ CD4 T cells is reduced in obesity, pre-diabetes and T2D." (PMID 27095356, 2016). "Second, we could not assess the impact of other important variables/comorbidities on mortality, such us malnutrition, diabetes, occupation or immunosuppression (CD4 counts), which would provide further characterization of TB mortality factors." (PMID 27198545, 2016). "The non-obese diabetic NOD mouse develops insulin-dependent diabetes mellitus spontaneously as a consequence of an autoimmune process in the presence of pathogenic CD4+ T cells that typically exhibit Th17 cell phenotypes." (PMID 27165305, 2016). "Among participants not using diabetes medication, higher memory and lower naive CD4+ cells were associated with higher fasting glucose concentrations (p<0.05, adjusted for age, sex, and race/ethnicity)." (PMID 26458065, 2015). "In this line of avaliation, 167 PCOS patients compared to 102 controls were evaluated and such study aimed at identifying coronary instability and diabetes mellitus type 2 through the frequency of CD4 (+) CD28 (null) lymphocytes that express the level of involvement by these morbidities." (PMID 26104466, 2015). "Moreover, these PLN memory CD4+ T cells release increased levels of IL-17 in response to diabetes-related antigens, proinsulin, and GAD65." (PMID 26843788, 2015). "HIV exposure group (intravenous drug user versus all others), gender, hepatitis C coinfection, age, nadir CD4 count (≤200 cells/mm3), baseline eGFR, hypertension, diabetes, and prior CVD at baseline were all significant predictors of CKD and were included in the risk score model." (PMID 25826420, 2015). "It has been shown that in the neonatal thymectomy NOD model of T1D, gut intraepithelial CD8+γδ T cells can prevent development of diabetes, and proper development of intraepithelial γδ T cells is required for induction of regulatory CD4+CD25+ T cells by oral insulin." (PMID 24728138, 2014). "Pancreatic histology revealed that the induction of diabetes upon transfer of mature DCs was associated with significantly increased infiltration by CD8+ cells (P<0.05 for 5–15% infiltration and >50% infiltration levels) and, to a lesser extent, CD4+ cells." (PMID 24647761, 2014). "Interestingly, blockade of ICOS and PDL1 was found to negate the regulatory effect of the CD4+ Type II NKT cells in the pancreatic lymph node leading to a sudden development of diabetes." (PMID 24586872, 2014). "The role of CD4+CD25+ regulatory T cells in diabetes mellitus is still being debated." (PMID 25279317, 2014). "Moreover, significantly more CD4+CD44high T cells were sorted from the pancreases of prediabetic than of diabetic mice, suggesting that rare CD4+CD44high clonotypes are lost between 10 weeks of age and diabetes onset." (PMID 24146886, 2013). "Furthermore, generation of IL-5-producing GAD65-specific CD4+ T cells was shown to protect NOD mice from diabetes development." (PMID 23390544, 2013). "In this study age, gender, taking ARV agents, medication with anti-hyperglycemic drugs, diabetes, smoking, alcohol consumption, CD4 cell, viral load and FPG level were not significant risk factor for high LDL (p > 0.05)." (PMID 23947428, 2013). "It is, however, pivotal to know whether the variable T-cell frequency (and the concomitant change of the CD4+/CD8+ ratio) are genetically inherited and linked to diabetes susceptibility." (PMID 23717591, 2013).
diabetes (continued). "Five (20%) patients had immunocompromising conditions: pulmonary sarcoidosis (CD4 count of 92 cells/mm3), diabetes and liver transplant, an unspecified immunocompromising condition, active lung cancer (patient receiving chemotherapy), and congenital hyper-IgE syndrome (Job syndrome)." (PMID 24050410, 2013). "The prevalence of diabetes increased with decreasing CD4 count (P = 0.032)." (PMID 23394285, 2013). "The evidence suggests that the initiation of the autoimmune response occurs within the draining pancreatic lymph node (PLN) since removal of the PLN prevents diabetes and several studies have shown that the initial proliferation of islet-specific CD4 and CD8 T cells takes place in the PLN." (PMID 24367363, 2013). "We also show that many CD4+CD44high clonotypes present in the islets of diabetic mice were already present in the prediabetic mice, suggesting that potentially diabetogenic clonotypes are resident in the pancreas before the onset of diabetes." (PMID 24146886, 2013). "Autoreactive memory CD4+ T cells play a critical role in the development of type 1 diabetes, but it is not yet known how the clonotypic composition and TCRβ repertoire of the memory CD4+ T cell compartment changes during the transition from prediabetes to diabetes." (PMID 24146886, 2013). "Inasmuch as CD4+ T-cells appear to mediate T1D via macrophages in the NOD.scid adoptive transfer model, failure of splenocytes from TSA treated mice to transfer diabetes in NOD.scid mice is likely to be due to altered transcription of these genes in CD4+ T-cells as well as in macrophages." (PMID 23383062, 2013). "Moreover, it have been shown that intraepithelial CD8+γδ T cells prevent diabetes, and intraepithelial γδ T cells are required for induction of regulatory CD4+CD25+ T cells by oral insulin, in the neonatal thymectomy NOD mouse model of T1D." (PMID 22428018, 2012). "Furthermore, old age, small body weight, low baseline CD4 count, high HIV viral load, high eGFR, low serum creatinine, concurrent use of nephrotoxic drugs, hepatitis B infection, and diabetes mellitus were associated with renal dysfunction." (PMID 22242194, 2012). "However, we found that the unstimulated cells from diabetic patients with T1D and T2D diabetes expressed intracellular RAGE on CD4+ and CD8+ T cells." (PMID 22509345, 2012). "Intraperitoneal injection of a long-lived noncytolytic murine IL-10/Fc fusion protein into young NOD mice prevents insulitis and diabetes by blocking the production of proinflammatory cytokines and IFNγ, and IL-10-transduced islet-specific CD4+ T-cells prevent diabetes transfer in NOD mice." (PMID 21716731, 2011). "Defects on the T-cell developmental program have been linked to many diseases, including a proposed contribution to diabetes susceptibility in non-obese diabetic mice, with CD4+CD8+ blasts that have abnormally high expression of IL-7Ralpha, and c-Kit." (PMID 21152067, 2010). "Such defects have been linked to many diseases, including a proposed contribution to diabetes susceptibility in non-obese diabetic mice, with CD4+CD8+ blasts that have abnormally high expression of IL-7Ralpha, and c-Kit." (PMID 21152067, 2010). "We found that, although all expanded Tregs showed suppressive functions in vitro, only p524 (GAD524–538)-expanded CD4+CD25+ T cells inhibited diabetes development in the co-transfer models, while p509 (GAD509–528)- or p530 (GAD530–543)-expanded CD4+CD25+ T cells had no such effects." (PMID 19759824, 2009). "In this setting, we also examined whether IL-10/TGF-β cytokines played an essential role in p524-expanded CD4+CD25+ T cell-mediated delayed development of diabetes." (PMID 19759824, 2009). "The data presented in this study indicate that this failure to inhibit transfer of diabetes may be attributed to the differential cytokine profiles of expanded CD4+CD25+ T cells." (PMID 19759824, 2009).